PCNA (proliferating cell nuclear antigen)
Diseases named in the same sentence as PCNA in open-access papers (continued):
Sharing a sentence is not in itself a finding about the gene and the disease.
cancer (continued). "Moreover, Choi and colleagues reported that açaí treatment down-regulated myeloperoxidase (MPO) and proinflammatory cytokines (TNF-α, IL-1β and IL-6), inhibited cyclooxygenase 2 (COX-2), PCNA and Bcl-2, and increased Bad and cleaved caspase-3 expression in an experimental model of cancer colon." (PMID 29966007, 2018). "PCNA responds to DNA damage by providing an error-free pathway and so adding inhibitors designed to target modified PCNAs could be used in conjunction with anti-cancer therapeutics." (PMID 30406112, 2018). "The possible molecular mechanism may involve activation of the Ras/ERK1/2 mitogen-activated protein kinase pathway to elicit cell cycle arrest by inducing the cyclin-dependent kinase inhibitors, p21(WAF) and p27(kip1), to inhibit PCNA and Ki-67 in cancer cell proliferation." (PMID 28740192, 2017). "Therefore, PCNA is widely considered as a biomarker for cancer progression and prognosis." (PMID 27806724, 2016). "Thus, the L-IVP strain causes a decrease in the number of mitoses in A431 carcinoma, however, it does not influence number of cells expressing Ki-67 and PCNA proteins." (PMID 26771631, 2016). "An alteration in PCNA structure might contribute to DNA-damage accumulation in cancer cells." (PMID 26557712, 2015). "In the future it would be very interesting to screen different human cancers for additional WDR48 mutations that might not only be defective in maintaining PHLPP1 function but also other substrates such as BRCA1, FANCD2, H2A/H2B, PCNA, and notch receptor." (PMID 24145035, 2013). "Notably, the presence of PCNA has been recently described in the cytosol of cancer cells." (PMID 23181059, 2012). "Moreover, PCNA and Ki-67 are used to determinate the proliferating activity of cancer cells." (PMID 20416104, 2010). "Endogenous and exogenous DNA damage can damage rapidly proliferating cancer cells; however, these cells can bypass DNA damage to maintain genomic stability and survive via the TLS pathway mediated by PCNA K164 monoubiquitination." (PMID 40025006, 2025). "We examined the expression levels of cyclin B, Cdk1, cyclin D1, PCNA, JAK1, STAT3, and other cancer pathway components." (PMID 40350446, 2025). "Among these drivers, RAS, PCNA, and MDM2 have become critical targets due to their roles in a broad-spectrum of cancer biology, e.g., cell proliferation, survival, and genomic stability." (PMID 41170373, 2025). "The expression of proliferating cell nuclear antigen (PCNA) and nuclear antigen (Ki‐67) was examined to elucidate the mechanisms of ZQJ29 on cancer development." (PMID 40387570, 2025). "Not all cancers may be equally susceptible to PCNA-targeted therapy." (PMID 41170373, 2025). "Suppression of PCNA impaired Olaparib-induced overexpression of PARP1 and RAD51, thereby reversing the resistance of cancer cells to Olaparib." (PMID 40313621, 2025). "Thus, we speculated that PCNA inhibition could impair cancer stemness in HNSCC." (PMID 41024256, 2025). "CHAF1A facilitates PCNA K164 monoubiquitination mediated by RAD18, thereby promoting the recruitment of Y-family DNA polymerases and enhancing cancer cell resistance to DNA damage." (PMID 40025006, 2025). "CCT4 expression was positively correlated with oncogenic proteins involved in cell proliferation and survival, including PCNA, Cyclin B1, FOXM1, across multiple cancer types." (PMID 41403933, 2025). "Our data provide unique insights into RAD18-driven PCNA monoubiquitination and the regulation of this process by MAGEA4 in cancers." (PMID 38448672, 2024).
cancer (continued). "In summary, 7-KSS application significantly reduced cell viability, suppressed proliferating cell nuclear antigen, S1P, p-ERK, and p-NF-κB p65 protein levels while increasing ceramide amounts and apoptotic cell numbers in cancer cells." (PMID 39065711, 2024). "Recently, researchers have developed a small molecule inhibitor of PCNA called AOH1996, which has the potential to be developed as a broad-spectrum anti-cancer drug." (PMID 38556560, 2024). "In a study published in Cancer Prevention Research and Treatment, the presence of apoptotic markers, cyclin D1, VEGF, and proliferating cell nuclear antigen (PCNA), was assessed by performing the regression of renal carcinogenesis." (PMID 39619995, 2024). "Literature shows that many cancer types express de novo, or overexpress, IR ligands (such as BST2, PCNA, CAECAM-1 and modified surface carbohydrates) which often represent a strong predictor of poor outcome and metastasis." (PMID 38504978, 2024). "We also spiked in a panel of 41 negative control sgRNAs (targeting nonhuman genes such as Luc, LacZ, Ren and Rosa26 and scrambled sequences) and 27 positive control sgRNAs (targeting cancer-essential genes such as MYC, PCNA and RPA3)." (PMID 38316881, 2024). "PCNA is essential for DNA replication, and MMP9 is related to cancer cell metastasis, both of which contribute to CRC development." (PMID 37347740, 2023). "The antiproliferative actions of açaí, such as the downregulation of proliferating cell nuclear antigen (PCNA), p63, and Ki-67, have been shown to decrease the persistence, proliferation, and metastasis of different cancerous tumors." (PMID 36839349, 2023). "In keratinocytes and cancer cell lines, GRHL2 expression levels correlated with increased and decreased PCNA expression after overexpression and knockdown, respectively." (PMID 37745294, 2023). "In particular, malignant tumors, such as adenocarcinoma, TML, and TML lung metastases, were more strongly stained with PCNA." (PMID 36608059, 2023). "For anti-cancer experiments, the test compounds showed comparable docking scores with the positive control (Doxorubicin) for both target proteins, i.e., BRCA and PCNA." (PMID 37496047, 2023). "By methylating the Proliferating Cell Nuclear Antigen (PCNA) protein, SETD8 induces proliferation of numerous cancer cell lines." (PMID 37758718, 2023). "According to reports, Myr inhibits the proliferation of various cancer cells through multiple signaling pathways, including PI3K/AKT, PAK1/MEK/ERK1/2, cyclin D1/PCNA, STAT3 and so on." (PMID 35646711, 2022). "The MCODE analysis identified gene clusters for each cancer type with MYC, PCNA, PARP1, IDH1, FGF10, PTEN, and CCND1 as hub genes with high connectivity." (PMID 35001007, 2022). "On the other hand, none of the dHCPPIs was the same for all cancer types studied, and five interactions were the same in at most seven different cancers (i.e., CAV1-CTNNB1, COL1A1-IGFBP3, LDHA-LDHB, PCNA-GAPDH, and PSMB7-PSMB3)." (PMID 36422095, 2022). "Treatment with 100 mg/kg corylin in the AOM/DSS mice led to significantly decreased cancer stem cell and intestinal epithelial cell proliferation, including LGR5, CD44, Ki67, PCNA, BrdU, and Cyclin D1 levels, compared with the AOM/DSS group." (PMID 35269806, 2022). "RAD18 is the E3 ligase that monoubiquitinates PCNA, a central signaling event in TLS and CYLD is a deubiquitinase involved in cancer and required for efficient TLS, as we have previously reported." (PMID 34203408, 2021).
cancer (continued). "S100A2, TGFA, MET, PCNA, SCD, GDF15, and PAI1 act as oncogenes by promoting cancer metastasis or proliferation 24-30." (PMID 34131400, 2021). "ADAMTS9-AS1 interference enhanced cancer proliferation and invasion, facilitated levels of KI67, PCNA, MMP-9 and MMP-2, and activated the JAK STAT signaling pathway." (PMID 34900984, 2021). "It was revealed that apelin could promote cancer cell proliferation by increasing expression of factors involved in cell proliferation including cyclin D1, Ki-67, proliferating cell nuclear antigen (PCNA), and activating pathways like JAG1/Notch3, ERK1/2, and PI3K/Akt." (PMID 33912466, 2021). "Cluster 4 showed high expression of cell cycle‐related genes for markers such as PCNA, MCM5, MKI67, STMN1, and CDK1, probably owing to the immune response to cancer neo‐epitopes." (PMID 33513276, 2021). "USP1 function as an oncogene by interacting with DNA repair signal through PCNA and FANCD2, USP4 promote cancer progression by deubiquitinating TRAF2 and TRAF6 and thereby regulating the TGFβ signaling pathway." (PMID 34545063, 2021). "Thus, the Y211 site of PCNA may be an effective target to develop cancer therapy." (PMID 34671219, 2021). "It has been found that GSDME-mediated pyroptosis induced cancer cells proliferation and PCNA(proliferating cell nuclear antigen) expression through the ERK1/2 pathway by releasing intracellular HMGB1, which in turn promoted the development of CAC." (PMID 34381721, 2021). "We observed that samples with high chromatin accessibility of CERES have high expression of CDKN1C, accompanied by low expression of genes involved in cancer cell proliferation (MKI67 and PCNA) and aggressiveness (FOXM1)." (PMID 34272384, 2021). "Cluster 3 was highlighted by the significantly increased transcripts of proliferating marker genes, including MKI67, PCNA and DNA Topoisomerase gene, TOP2A, suggesting activated cell proliferation in this cancer cell cluster." (PMID 34055623, 2021). "Of note, consistent with published data that actively proliferating cancer cell lines display an elevated level of WRN45, we detected substantially enhanced WRN immunofluorescence in PCNA-positive cells as compared to PCNA-negative cells." (PMID 34772932, 2021). "Like APE2, PCNA, BRCA2 and XRCC1 were also significantly upregulated in all cancer types except prostate." (PMID 32111912, 2020). "This overexpression likely results in the increased monoubiquitination of PCNA, inappropriately activating TLS to drive cancer mutagenesis." (PMID 33023096, 2020). "Y211-phosphorylated PCNA facilitates error-prone DNA replication and the suppression of the MMR (mismatch repair) mechanism, which enhances cancer development and progression." (PMID 32276417, 2020). "We have shown that APE2 expression is positively correlated with the expression of PCNA, APE1, PARP1, XRCC1, Chk1, and Chk2 across all six cancer types analyzed in this work." (PMID 32111912, 2020). "Following the observation of an increased IGF1R/PCNA colocalization in clinical tumors, we performed a similar PLA staining for Rad18 and PCNA on a subset of the clinical cancer panel (n = 16)." (PMID 32701997, 2020). "Across all 6 cancer types, APE2 expression was significantly positively correlated with the expression of PCNA, APE1, PARP1 and XRCC1 yet expression ranges varied per cancer type and gene-gene pair." (PMID 32111912, 2020). "Accordingly, the treatment with CADMN showed down-regulation in the expression of PCNA indicating an anti-proliferative effect, which was consistent with the findings of the proliferation suppression effects of CADMN on different cancer cells." (PMID 33316979, 2020). "We also found a significant correlation between IGF1R/PCNA and RAD18/PCNA colocalization in cancer tissue, indicating a possible link to TLS activation." (PMID 32701997, 2020).
cancer (continued). "Ki67 and Proliferating Cell Nuclear Antigen (PCNA) proteins are standard markers of cell proliferation, thus commonly used to help assess malignancy grades of cancer." (PMID 32677955, 2020). "While APE2 had a significant (α = 0.05) positive correlation with PCNA, APE1, XRCC1, PARP1, Chk1, and Chk2 across all 6 cancer types, groupings of DNA repair and DDR genes were found to be correlated with APE2 in different patterns in different cancer types." (PMID 32111912, 2020). "To study the activation of the DDT pathway in cancer tissue, we performed in situ PLA for IGF1R/PCNA colocalization in 35 tumors (29 primary and 6 metastases) from 30 patients." (PMID 32701997, 2020). "Previously, we have shown that in vivo inhibition of the functions of either PCNA or DNA polymerase alpha (which are key components of the replisome) by antibodies, strongly induced RS and the consequent phosphorylation of H2AX in cancer cells." (PMID 30871194, 2019). "Initial pharmacodynamics data analysis shows dose-dependent reduction of MYC, PCNA, and MCL-1 levels, all being relevant for cancer cell survival." (PMID 31253180, 2019). "Therefore, targeting PCNA could be an effective approach for treatment of cancer." (PMID 31600334, 2019). "VOPP1 (also known as Vesicular, Overexpressed in cancer, Prosurvival Protein 1 or EGFR-Co-amplified and Overexpressed Protein) expression is shown first in relation to EGFR expression, then to PCNA expression." (PMID 31857847, 2019). "Consistently, collagen I-induced upregulation of proliferation (PCNA), phosphorylated ERK1/2, EMT (vimentin and N-cadherin), cancer stem cell marker Nanog was markedly reduced in heat-exposed residual HCC cells pretreated with ERK1/2 inhibitor U0126." (PMID 30227844, 2018). "It has been shown that targeting PCNA with an APIM-peptide impaired cellular defense mechanisms and major signaling pathways, with the consequence of hypersensitivity of cancer cells to chemotherapies in vitro and in vivo." (PMID 29545934, 2018). "Inhibitors of bacterial (β-clamp) and eukaryal DNA clamps, proliferating cell nuclear antigen (PCNA), have been explored for use as antibacterial and anti-cancer drugs, respectively." (PMID 30406112, 2018). "PCNA is similar to the CMG in terms of its role in cell proliferation and acts as a marker for cancer." (PMID 29651420, 2018). "In agreement with our previous findings in U2OS cancer cells, PLK1 target phosphorylation remained undetectable during active DNA replication and only appeared when the bulk of PCNA foci disappeared." (PMID 30008317, 2018). "To examine the link between MELK and cell division in cancer, we compared the levels of MELK expression with five well-characterized proliferation markers: MKI67, PCNA, CCNB1, MCM2, and TOP2A." (PMID 29417930, 2018). "The proliferation index determined by cell cycle-related markers, such as antigen KI-67 (Ki-67) and proliferating cell nuclear antigen (PCNA), has prognostic value in cancer patients." (PMID 28106052, 2017). "Treatment of DU145cells with SPHK1 siRNA and CA for 48 h decreased cancer cell growth, and the inhibitory action of SPHK siRNA and CA on cell growth was confirmed by decrease in the abundance of Proliferating cell nuclear antigen (PCNA)." (PMID 28165392, 2017). "We also found that miR-200b-3p and miR-429-5p dually inhibited expression of PCNA, MMP2, and MMP9, protein biomarkers of cancer-cell proliferation and motility, in MDA-MB-231 and HCC1937 cells." (PMID 29156719, 2017). "The most commonly used markers, such as Ki-67 and proliferating cell nuclear antigen (PCNA), identify malignant cancer cells because their expression coincides with DNA synthesis." (PMID 27780919, 2016). "Similar to PCNA, overexpression of KIAA0101 can promote growth and invasion of cancer cells and predict poor prognosis in cancer patients." (PMID 27806724, 2016).
cancer (continued). "This study found that the elevated expression of LARP1 correlated positively with PCNA expression, suggesting that LARP1 mediated cancer cell proliferation." (PMID 27614686, 2016). "Pancreata of mice receiving combination treatment showed significantly fewer Dclk1-positive cancer stem-like cells, inhibition of COX-2, 5-LOX, PCNA, EGFR and β-catenin expression (p < 0.05–0.0002), increased p21 expression." (PMID 26429877, 2015). "Similar to the results of CSC marker genes, semiquantitative RT-PCR analysis showed that ADSCs strongly upregulate the growth-related genes in cancer cells, including MKI67 (4T1, 7.44 ± 2.43; CT26, 2.93 ± 0.29) and PCNA (4T1, 3.85 ± 1.02; CT26, 7.09 ± 1.54)." (PMID 25797257, 2015). "Immunohistochemistry analysis showed the down-regulation of PCNA and Bcl-2 proteins and the up-regulation of Bax protein after administration of EEAML compared with the cancer control group." (PMID 25860620, 2015). "We also found that IL-6 neutralization markedly diminished the up-regulation of MKI67 (4T1, 1.21 ± 0.22; CT26, 1.27 ± 0.31) and PCNA (4T1, 1.54 ± 0.9; CT26, 1.20 ± 0.46) induced by ADSCs in cancer cells." (PMID 25797257, 2015). "Expression of Beclin-1, PCNA, NET-1, Bcl-2, Bax, Survivin in cancer cells and CD34 in stromal microvessels were evaluated immunohistochemically in tissue microarrays comprising 103 cases of HCC and 57 matched adjacent nontumor liver tissues." (PMID 24885292, 2014). "Thus, the improved understanding of PCNA modification and its implications for DNA damage response may provide us with more insight into the mechanisms by which human cells regulate aberrant recombination events, and cancer initiation and development." (PMID 24765138, 2014). "Conversely, HDAC1, CCDN1, PCNA, CDX1, KRT18, CDX2 and CASP3 are all expressed at significantly lower levels in normal tissue compared to adenomatous polyp or carcinoma tissues." (PMID 25423035, 2014). "This further correlates RAGE to cancer cell proliferation and indicates that cell signaling initiated by RAGE leads to higher expression of both cyclinD1 and PCNA." (PMID 23579957, 2013). "Having established that ATX-101 is properly imported in HeLa cells and targets PCNA, we sought to identify ATX-101 sensitive cancer cell lines using proliferation assays." (PMID 23936203, 2013). "Proliferating cell nuclear antigen (PCNA) is a multifunctional protein essential for DNA replication and repair that is often overexpressed in cancer cells." (PMID 23936203, 2013). "As observed with hematoxylin and eosin (H&E) and PCNA staining, HGF injection led to more intense infiltration of cancer cells into the lung and liver of MDA-MB-436 xenograft-bearing mice than did the PBS injection." (PMID 22242160, 2012). "Proliferating cell nuclear antigen (PCNA) immunostaining and TUNEL were performed in surgical samples to determine the effects of chemotherapy on cancer cell proliferation and apoptosis, respectively." (PMID 22523546, 2012). "Proliferative program analysis in cancer cells revealed a fundamental impact of CDA-2 and PG on proliferation and apoptosis, including Bcl-2, Bcl-XL, cIAP1, Survivin, PCNA, Ki-67 proteins and TUNEL assays." (PMID 23284890, 2012). "The intensity of staining for Ki-67 (1:50; Zymed, San Francisco, CA, USA) and PCNA (1:100; DAKO, Glostrup, Denmark) was decreased in recurrent cancer cells in comparison to primary cancer specimens." (PMID 21092332, 2010).